IL1B (interleukin 1 beta)
Diseases named in the same sentence as IL1B in open-access papers (continued):
Sharing a sentence is not in itself a finding about the gene and the disease.
tumor (continued). "To further demonstrate PD-1/Al@OV’s ability to modulate the immune microenvironment, we measured tumor-secreted IL-1β, IL-6, and IFN-γ levels using ELISA." (PMID 39955603, 2025). "To further investigate the relevance of these findings and the interaction between PDAC and macrophages, we examined the effect of co-culturing PDAC tumor cells and macrophage-like cells on the induction of IL1B expression." (PMID 40634284, 2025). "Unlike traditional apoptosis and necrosis, pyroptosis is more effective in inducing the release of intracellular pro-inflammatory factors, such as IL-1β and IL-18, thereby promoting a robust inflammatory response and reducing tumor resistance." (PMID 40486906, 2025). "In support, the blockade of IL-1β in a mouse model of BC reversed immunosuppression and completely abrogated tumor progression in combination with anti-PD-1 antibodies, suggesting a pro-tumor role of AIM2 in BC." (PMID 40002808, 2025). "The expression of IDO1 can be triggered as a counter-regulatory response to cytokines released by tumor-infiltrating immune cells (such as IL-1β and IL-6), and can also be maintained through intrinsic oncogenic signaling in the tumor." (PMID 40137165, 2025). "Studies have found that tumor cell IL-1β drives tumor progression in TNBC, invasion, metastases, stemness, and EMT." (PMID 40868199, 2025). "ETBF releases BFT, prompting tumor and stromal cells to secrete interleukin (IL)-6, IL-1β, and IL-23." (PMID 40940828, 2025). "IL-1β has dual functions in promoting and suppressing tumor progression and cell cycle arrest in PCa." (PMID 40427694, 2025). "Tumor-associated neutrophils have also been identified as a major source of IL-1β within the tumor microenvironment." (PMID 41087719, 2025). "The attenuated hematopoietic cell-derived IL-1β and IL-18 at the tumor site of Nlrp3-knockout (Nlrp3−/−) mice are found to be the key to inflammation and tumorigenesis." (PMID 40141358, 2025). "TNF-α and IL-1β, key pro-inflammatory cytokines, are known to enhance angiogenesis, tumor invasion, and resistance to apoptosis." (PMID 40143078, 2025). "IL-6 and IL-1β activate STAT3/NF-κB pathways in tumor cells, enhancing proliferation, invasion, and stemness." (PMID 41007766, 2025). "In cancer, activation of the NOTCH signaling pathway increases the production of cytokine IL-1β and chemokine CCL2, which induce inflammation and recruitment of tumor-associated macrophages." (PMID 40863244, 2025). "In serum, the levels of TNF-α and IL-1β were notably higher in the Tumor group in comparison to the Con group, and there was a significant downregulation in the PVSO group." (PMID 40993108, 2025). "An additional study showed that depletion of IL-1β resulted in tumor regression and reduction in tumor-infiltrating neutrophils, promoting an immunosuppressive TME and resistance to angiogenic therapy." (PMID 39858071, 2025). "IL-1β enhances this effect by promoting the interaction between tumor cells and immune cells in the tumor microenvironment." (PMID 40837560, 2025). "NRF2 promotes metastasis by regulating epithelial-mesenchymal transition and modulating cytokine production—suppressing pro-inflammatory cytokines (e.g., IL-6, IL-1β) while inducing tumor-promoting ones like IL-11." (PMID 41187427, 2025). "Among the analysed cytokines, IL-1β (68.9%) and IL-6 (67.8%) showed the highest proportions of elevated expression, suggesting their prominent role in the tumour microenvironment." (PMID 41465261, 2025). "Among these, CTSS was uniquely identified as the lysosomal protease capable of cleaving GSDMD, IL‐1β, and IL‐18 independently of caspase‐1, establishing a novel pathway of tumor‐specific pyroptosis induction." (PMID 40539828, 2025). "Deletion of Jun in Pten-deficient mice results in reduced immune cell attraction, activation of Stat3 and IL-1β production, which accelerated tumour growth." (PMID 39859271, 2025).
tumor (continued). "In a lung cancer model, MCC950 was found to reduce IL-1β secretion, suppress angiogenesis, and inhibit metastasis through NLRP3 pathway inhibition in tumor-associated macrophages (TAMs)." (PMID 40877572, 2025). "Reciprocally, PRDX1 ablation in macrophages restrains M2 polarization and enhances T‐cell‐mediated anti‐tumor immunity by promoting the secretion of inflammatory factors (IL‐1β and TNFα) via activation of JAK‐STAT1/NF‐κB signaling pathways." (PMID 41306557, 2025). "While curdione and borneol inhibited inflammatory factors such as IL-6 and IL-1β expression in macrophages, TNF-α and CASP1 mRNA expression levels were up-regulated, which are associated with anti-tumor and anti-viral responses." (PMID 39911394, 2025). "In particular, the activation of NLRP3 in dendritic cells (DCs) showed an anti-tumor activity via IL-1β/Th1/IFNγ." (PMID 39857785, 2025). "Inflammation plays a critical role in HNC progression, with elevated levels of pro-inflammatory cytokines such as TNF, IL-6, IL-8, and IL-1β contributing to tumor development." (PMID 40733296, 2025). "A large number of inflammatory factors (e.g., IL-1β and IL-18) are released after pore formation, thereby altering the tumor microenvironment, and triggering a strong anti-tumor immune response." (PMID 40011473, 2025). "M1 macrophages, activated by pro-inflammatory signals like interferon-gamma (IFN-γ), IL-1β, and IL-12, exhibit anti-tumor activity by enhancing cytotoxic T-cell responses and directly killing tumor cells." (PMID 40565133, 2025). "In PC, the genes ESR1 and SRC exhibited overexpression in tumor tissues, whereas IL1B and CTNNB1 showed reduced expression." (PMID 41186627, 2025). "Further, innate immune activation, including interferon β, IFIT1, and inflammatory factor IL-1β, was observed in HeLa tumor cells." (PMID 41392286, 2025). "Notch signaling can activate monocytes and macrophages by driving CCL2 and IL-1β production, while promoting anti-tumor immunity by regulating TGFβ receptor and uPA production." (PMID 40165901, 2025). "Compared with surgical margins, tumour tissues showed a characteristic inflammatory shift, with markedly increased IL-1β and IL-6 and relatively reduced TNF-α, IFN-γ, IL-12 and IL-2." (PMID 41465261, 2025). "Among them, IL-1β and TNF-α contribute to tumor chemotherapy resistance and are associated with poor prognosis of chemotherapy." (PMID 39972411, 2025). "lncGALM also contributes to LSEC apoptosis by stabilizing IL‐1β mRNA in metastatic tumor cells, thereby inducing endothelial barrier opening to facilitate transendothelial tumor cell migration." (PMID 40027151, 2025). "Efferocytosis directly activates signaling of NLRP3 inflammasome, thereby driving IL‐1β secretion, which promotes tumor growth." (PMID 39748782, 2025). "It leads to interleukin-1β (IL-1β) secretion and activation of tumor antigen-specific, interferon γ (IFNγ)-producing CD8+ T cells." (PMID 41209313, 2025). "Overexpression of IFI16 has been implicated in the activation of the inflammasome, leading to the induction of IL-1β production in the tumor microenvironment of PAAD." (PMID 40386782, 2025). "Within the tumor microenvironment, tumor cells and associated stromal cells, such as macrophages and fibroblasts, secrete pro-inflammatory cytokines (e.g., IL-6, TNF-α, IL-1β)." (PMID 39836268, 2025). "Concurrently, to determine if 2-DG induces pyroptosis in vivo, expression of caspase-3, GSDME, IL-18, and IL-1β was analysed in tumor tissues." (PMID 41415273, 2025). "It has been reported that IL-6 and IL-1β can stimulate tumor cells to express CD274 (PD-L1) proteins via activating the STAT3 signaling pathway, thereby facilitating tumor cell immune escape." (PMID 39911394, 2025). "Tumor microenvironmental factors such as IL-1β, IL-6, TNF-α, and IFN-γ, promote IMCs accumulation, inhibit their differentiation, and activate their immunosuppressive functions, at which point they are referred to as MDSCs." (PMID 40822347, 2025).
tumor (continued). "Sorafenib enhances NK activity via macrophage-derived cytokines (IL-12, IL-18, IL-1β), suggesting NK activation contributes to its anti-tumor efficacy." (PMID 40242773, 2025). "IL-1β, in cooperation with IL-6 and low-dose TGF-β, biases Th17 cells toward a pathogenic profile that favors inflammation, angiogenesis, and tumor progression." (PMID 41181112, 2025). "The cluster 6 monocytes were defined by high expression of multiple pro-tumor genes (IL1B, SERPINB2, CCL2, CXCL1, CXCL5, CXCL8, CCL3, CCL20)." (PMID 40176808, 2025). "Proinflammatory cytokines, such as tumor necrosis factor (TNF), IL-6, and IL-1β, typically drive tumor progression by enhancing tumor cell proliferation, survival, and invasive potential, as well as promoting angiogenesis." (PMID 40563367, 2025). "Since IL-1β, IL-6, and TNF-α are well-established mediators of tumor-associated inflammation, their downregulation is mechanistically relevant." (PMID 41470183, 2025). "Elevated IL-1β serum levels are strongly correlated with disease progression, highlighting the clinical relevance of IL-1β as a potential prognostic marker in neoplastic disease." (PMID 39858071, 2025). "By releasing IL-1β, monocytes promote E-selectin expression on endothelial cells, enhancing the adhesion of tumor cells to the vascular endothelium." (PMID 40427136, 2025). "This suppression of NF-κB activity directly translates into reduced expression of pro-inflammatory cytokines such as TNF-α, IL-6, and IL-1β, which are fundamental for tumor progression, angiogenesis, and immunosuppression." (PMID 41302515, 2025). "Cytokines like “tumor necrosis factor (TNF-α), IL-1 beta (IL-1β), and interleukin-6 (IL-6)” are released into the tumor microenvironment by the inflammasome from necrotic cells." (PMID 41068541, 2025). "IL-1β, although pro-inflammatory, can contribute to tumor progression or immune suppression and Eotaxin is generally linked to eosinophil recruitment and type 2 immunity." (PMID 40630200, 2025). "Synergistically, these perturbations activate NF-κB/STAT3 signaling, generating a pro-inflammatory cytokine milieu (IL-6, TNF-α, IL-1β) that promotes tumor progression through autocrine-paracrine cascades." (PMID 40919140, 2025). "M2 TAMs increase angiogenesis by upregulating angiogenesis-associated genes such as VEGF, PDGF, and PGE2, or via molecules CXCL12, IL-1β, IL-8 and Sema4d, leading to tumor progression." (PMID 40165901, 2025). "This aligns with evidence on NLRP3 inflammasome activation in tumor progression via IL-1β and IL-18 maturation." (PMID 41373809, 2025). "Currently, it is believed that tumor cells produce a significant amount of pro-inflammatory cytokines, including IL-1β and IL-6, as they adapt to the surrounding environment." (PMID 40959570, 2025). "In the context of PC, tumor cell expression of IL-1β in vivo was driven by microbial-dependent activation of Toll-like receptor 4 (TLR4) signaling and subsequent engagement of the NLRP3 inflammasome." (PMID 40948749, 2025). "IL-1β in the TME can result in an immunosuppressive environment that supports tumor proliferation and metastasis." (PMID 39858071, 2025). "Polarization to N1 (anti-tumor, IFNβ/IL-1β-driven) or N2 (pro-tumor, TGF-β/IL-6/7/8-driven) phenotypes influences tumor dynamics." (PMID 40242773, 2025). "Blockade of STAB1 (with bexmarilimab) followed by transcriptomic analysis demonstrated that TAMs were reprogrammed to enhance production of IL1β, IFNγ, and TNFα; all pro-inflammatory and cytolytic killing of tumor cells." (PMID 41007347, 2025). "Compared with patients with low levels of both IL-6 and IL-1β, patients with high levels of both IL-6 and IL-1β have significantly shorter overall survival and progression-free survival, a lower tumor control rate, and a reduced high-dose intensity of GEM." (PMID 40948749, 2025).
tumor (continued). "In contrast, combination anti-IL-1β and anti-PD-1 slows primary tumor growth in a PDAC murine orthotopic model with liver metastasis tropism, but does not reduce liver metastasis rate." (PMID 39948655, 2025). "IL‐1β has been shown to prevent tumor cells from ferroptosis, and we found that IL‐1β conferred a resistance to ferroptosis in CIA‐FLS." (PMID 41255239, 2025). "The qPCR analysis of total mRNA from tumor tissues revealed significant upregulation of M1 markers Nos2, Il1b, and Il6, along with marked downregulation of M2 markers Mcr1, Arg1, and Il10." (PMID 39908200, 2025). "There are already mature clinical drugs for the treatment targeting IL1B (such as Anakinra and Canakinumab), and extensive research has been conducted in various inflammatory diseases, cardiovascular diseases, and tumor prevention." (PMID 41516018, 2025). "Recently, GLIS (50–200 μg/mL) was also reported to activate bone marrow-derived macrophages in tumor-bearing mice, which secreted the pro-inflammatory cytokines IL-1β, TNF-α, and NO to trigger higher antitumor activities." (PMID 40733125, 2025). "M1 macrophages, often referred to as “classically activated” macrophages, produce pro-inflammatory cytokines such as TNF-α, IL-1β, and IL-6, as well as nitric oxide (NO), and exhibit strong anti-tumor activity." (PMID 40328748, 2025). "In vitro experiments demonstrated that inhibiting IL-1B signaling with an IL-1B antibody significantly reduced tumor cell growth and invasion abilities." (PMID 40141426, 2025). "In hepatocellular carcinoma studies, WEHI-3 mimics tumor-associated macrophages (TAMs) to investigate how M2 polarization supports tumor progression through IL-1β secretion and angiogenesis promotion." (PMID 40909285, 2025). "On the other hand, glycolytic metabolism fosters the PD-L1 expression on macrophages by causing the secretion of pro-inflammatory cytokines TNF-α and IL-1β, leading to tumor immune escape." (PMID 39897050, 2025). "In PDAC, IL-1β released by TAMs suppressed the expression of 15-hydroxyprostaglandin dehydrogenase (15-PGDH), an enzyme inversely associated with tumor advancement, presence of lymph node metastasis and nerve invasion, and poor prognosis of patients." (PMID 40083710, 2025). "Mechanistically, LCP1 expression and phosphorylation were induced by EGFR signaling through PI3K/AKT and ERK pathways, and further enhanced tumor aggressiveness via JAK2/STAT3-mediated IL-1β production." (PMID 41044643, 2025). "Cytokines such as TNF-α, IL-1β, IL-2, and IL-6 can enhance tumor growth, angiogenesis, metastasis, and invasion by promoting the survival and proliferation of tumor cells through activation of the NF-κB pathway." (PMID 40172365, 2025). "Inflammatory molecules such as IL-6, TNF-α, and IL-1β send signals that help tumor cells take in more glucose, produce more fats, and change how they use oxygen for energy." (PMID 41514860, 2025). "Systemic inflammation, driven by proinflammatory cytokines such as tumor necrosis factor-α (TNF-α), interleukin (IL)-6, and IL-1β, produced by both the tumor and the host, is involved in the pathogenesis of cancer cachexia." (PMID 40136406, 2025). "Recently a lot of studies aim to explore the role of IL-1β in inflammatory microenvironment and tumor immunity and the potentially correlation with this molecule and different clinical-pathological parameters in OSCC." (PMID 41560727, 2025). "To further investigate how anti-IL-1β and anti-PD-1 treatment modulates the tumor microenvironment, we performed flow cytometry analysis of tumor infiltrating leukocytes (TILs) from primary orthotopic tumors for both the KPC-4545 and the KPC-3403 model." (PMID 39948655, 2025). "Excess secretion of pro-inflammatory cytokines (e.g. IL-6, IL-1β, TGFα) by immune cells is critically involved in tumour cell avoidance of immune surveillance in the tumour microenvironment as well as in inflammation." (PMID 41023585, 2025).
tumor (continued). "Mechanistic studies indicate that GSDME-mediated pyroptosis can promote tumor antigen presentation and enhance T cell infiltration by releasing inflammatory factors such as IL-1β and IL-18, thereby improving the tumor immune microenvironment." (PMID 40568597, 2025). "Tumour-derived small extracellular vesicles (TEVs) from cells treated with IL-1β have been shown to activate a5β1 signalling, resulting in the upregulation of vimentin and SMAD3, cell migration and the EMT." (PMID 41148809, 2025). "CCL12, another chemokine expressed in the PMN, attracts Mo-MDSCs to the site before metastasis, prompting them to secrete IL-1β, which stimulates E-selectin expression and facilitates tumor cell attachment to the endothelium." (PMID 40427136, 2025). "First, neutrophils generate reactive oxygen species (ROS) inducing tissue and DNA damage, thus facilitating carcinogenesis, and further enhancing tumor metastasis through modulation of cytokines such as IL-1β." (PMID 40761249, 2025). "By inhibiting IL1B, production of inflammatory mediators can be reduced, weakening the pro-inflammatory state in tumor microenvironment, thereby inhibiting tumor progression." (PMID 40535567, 2025). "The activation of the AIM2 inflammasome by viral stimuli and elements within tumor microenvironment (TME) facilitates the secretion of IL-1β." (PMID 40386782, 2025). "IL-1β can exert anti-tumor effects by preventing metastatic cells from colonizing the metastatic site, thus inhibiting metastasis." (PMID 40427694, 2025). "TAMs generally exhibit two polarization states: M1 (classically activated, tumoricidal) enhance antitumor immunity by secreting TNF‐α, IL‐1β, and IL‐6, and producing nitric oxide and ROS, directly killing tumor cells and inhibiting tumor growth." (PMID 40900811, 2025). "The role of IL-1b in cancer is controversial, as it has been reported to induce Th1 and Th17 to strengthen the anti-tumor effect." (PMID 40427694, 2025). "Across multiple preclinical tumor models, RT has been shown to increase the expression of cytokines such as IL-1β, GM-CSF (CSF2), and G-CSF (CSF3), along with chemokines including CXCL1, CXCL2, CXCL5, CCL2, and CCL5." (PMID 40805288, 2025). "The pro-inflammatory cytokines TNF-α, IFN-γ, and IL-1β were significantly elevated following tumor induction." (PMID 41301523, 2025). "The genes encoding the most consistently differentially secreted cytokines, including IL-1RN, IL-1β, and IP10, are highly expressed in ISG and IL1B monocytes and up-regulated in the tumor microenvironment." (PMID 40668918, 2025). "Preclinical studies demonstrate that IL-1β inhibition synergizes with immune checkpoint inhibitors to enhance anti-tumor efficacy in murine models, likely by reversing TME-mediated immune suppression." (PMID 40563367, 2025). "Co-blocking of TIGIT and IL1β activated anti-tumor immunity, inhibited bone metastasis of BC, and improved the survival rate." (PMID 41181119, 2025). "On the other hand, a tumor-promoting role of IL-1β has been also well established over the years, as discussed here." (PMID 39858071, 2025). "Current strategies mainly focus on inhibiting tumor‐driven pathways that promote excessive lipid uptake and metabolism in NK cells, particularly the IL‐1β signaling pathway and the PPAR‐γ pathway." (PMID 40959206, 2025). "The caspase-1 inhibitor VX-765 has shown anti-tumor effects through the inhibition of pyroptosis and reduction in IL-1β secretion in non-small cell lung cancer (NSCLC) models." (PMID 40141358, 2025). "Mainly, IL-6 and IL-1β are produced by infiltrated mononuclear cells, stimulating the release of TNF and angiogenic factors such as VEGF, which are implicated in tumour initiation and progression." (PMID 41440367, 2025). "As expected, we observed that β-glucan treatment induced a higher level of IL-1β, IL-6, and IL-12p70 in tumor microenvironment, and the enhanced cytokines production was inhibited by alisertib." (PMID 40920087, 2025).